MTOR (mechanistic target of rapamycin kinase)
Diseases named in the same sentence as MTOR in open-access papers (continued):
Sharing a sentence is not in itself a finding about the gene and the disease.
Respiratory tract infection (5 papers, 2019 to 2025). An infection of the upper or lower respiratory tract. "It was reported that oral RTB101, an mTOR inhibitor, increased interferon-induced antiviral gene expression and reduced laboratory-confirmed respiratory tract infections (RTIs) compared to placebo in adults over 65 years." (PMID 40901298, 2025). "Studies show that the mechanistic target of rapamycin (mTOR) inhibitors can improve antibody responses to flu vaccination and decrease respiratory tract infections in community-dwelling older adults." (PMID 36298617, 2022). "More recently, the same group reported that a combined therapy of RAD001 and BEZ235, a competitive mTOR inhibitor, significantly reduced the annualized rate of respiratory tract infections in adults aged ≥65 years." (PMID 33123152, 2020).
rosacea (5 papers, 2021 to 2024). A chronic erythematous skin disorder that affects the face. "Here, we revealed that the autophagy of keratinocytes was associated with the aberrant activation of mTOR signals and contributed to the progression of rosacea." (PMID 36937834, 2023). "However, the underlying mechanism of mTOR signaling in rosacea still needs to be elucidated." (PMID 36937834, 2023). "The GO analysis revealed the enrichment of these target genes in rosacea-related, autophagy-related, and mTOR-related pathways." (PMID 36937834, 2023). "Meanwhile, topical administration of rapamycin (mTOR inhibitor) ameliorated clinical lesions in rosacea patients." (PMID 36937834, 2023). "In this study, an upregulated mTOR pathway in the epidermis of rosacea patients was confirmed using GSVA." (PMID 36937834, 2023). "The mammalian target of rapamycin (mTOR), as a serine/threonine protein kinase, has been reported to promote skin inflammation in rosacea." (PMID 37780385, 2023). "Previous studies demonstrated that mTOR signaling takes part in numerous cutaneous diseases, especially rosacea." (PMID 37780385, 2023). "Subsequently, WGCNA revealed the potential regulation of mTOR signaling on autophagy in the epidermis of rosacea." (PMID 36937834, 2023). "Next, we used WGCNA to identify the rosacea-related and mTOR pathway-related genes in the epidermis of rosacea." (PMID 36937834, 2023). "Studies with RNA-sequencing of lesioned skin from rosacea patients identify mTOR signaling as a critical pathway in the pathogenesis of rosacea." (PMID 35938153, 2022). "Topical Rapamycin, an inhibitor of mTOR, has shown clinical effectiveness in treating rosacea." (PMID 39351216, 2024). "Our previous work demonstrated the important role of hyperactivated mTOR signaling in rosacea." (PMID 36937834, 2023). "Next, autophagy was downregulated in the epidermis of rosacea, which was regulated by mTOR." (PMID 36937834, 2023). "Our previous study identified the important role of the mTOR pathway in rosacea; however, the potential mechanism remains unknown." (PMID 36937834, 2023). "Here, we focus on addressing the role of mTOR signaling in the pathogenesis of rosacea." (PMID 33734592, 2021). "Furthermore, our pilot clinical study showed that topical application of rapamycin significantly improved rosacea symptoms in patients, strongly suggesting the prospect of therapies targeting mTOR signaling in rosacea treatment." (PMID 33734592, 2021). "In consideration of the important role of the inflammatory response in the development of rosacea, we payed attention to the related KEGG pathways, among which mTOR signaling pathway was highlighted, indicating that this pathway might be involved in the pathogenesis of rosacea." (PMID 33734592, 2021). "In this study, based on the mTOR signal and autophagy-related genes, EGCG was predicted as a candidate drug for rosacea." (PMID 36937834, 2023). "Immunoblot analysis also showed that mTORC1 signaling was dramatically upregulated in the lesional skin of rosacea patients, which was not directly correlated with an increase in mTOR protein levels." (PMID 33734592, 2021). "Until now, however, there has been no proof of the direct connection between mTOR signaling and rosacea development." (PMID 33734592, 2021). "For example, activated TLR2 was reported to elevate rosacea-related kallikrein 5 (KLK5), subsequently producing the pro-inflammatory forms of antimicrobial peptide LL37, and LL37 interacts with TLR2 to activate mTOR signaling, eventually inducing the development of rosacea." (PMID 37780385, 2023).
selenium deficiency (5 papers, 2019 to 2024). A nutritional deficiency disease resulting from inadequate selenium levels in the body, which can lead to impaired function of selenoproteins essential for antioxidant defense and thyroid hormone metabolism. "In addition to selenium deficiency, elevated levels of the mechanistic target of rapamycin (mTOR) signaling proteins have been reported in psoriatic skin." (PMID 34707088, 2021). "Previous studies have reported that IGF1R played a positive role in weight gain and bone growth and development in broilers, and selenium deficiency in broilers could inactivate the IGF-1R/PI3K/Akt/mTOR pathway, reduce the growth rate of the spleen and the number of splenic lymphocytes." (PMID 32609751, 2020).
spinal muscular atrophy (5 papers, 2016 to 2022). A motor neuron disease that affect the muscles, and characterized by muscle weakness and atrophy resulting from progressive degeneration and irreversible loss of the anterior horn cells in the spinal cord (i.e., lower motor neurons) and the brain stem nuclei. "Previous studies also found that survival motor neuron (SMN) gene regulates axonal local translation via miR-183/mTOR pathway, which contributed to spinal muscular atrophy pathology." (PMID 27582688, 2016). "In mouse models of spinal muscular atrophy (SMA), deficiency of SMN protein leads to an accumulation of miR-183 and other miRNAs in the axon, and axonal synthesis of mTOR protein is impaired, leading to reduced mTORC1 and mTORC2 signaling and reduced axon outgrowth." (PMID 30618607, 2018). "In rodents, studies on Spinal Muscular Atrophy (SMA) led to the identification of CTRP3 (C1QTNF3, C1q/Tumor Necrosis Factor-related protein 3), which is secreted by muscle and promotes protein synthesis locally in motor neurons, via the activation of mTOR." (PMID 32982690, 2020).
vascular tumors (5 papers, 2017 to 2025). "Recently, rapamycin has emerged as an effective treatment for vascular tumors and malformations by inhibiting mTOR, and reducing VEGF production and cellular proliferation." (PMID 38883221, 2024). "Despite the potential efficacy in vascular tumors, mTOR inhibitors have not been investigated in clinical trials in angiosarcoma in people." (PMID 37368773, 2023).
Venous malformation (5 papers, 2020 to 2025). A vascular malformation resulting from a developmental error of venous tissue composed of dysmorphic channels lined by flattened endothelium and exhibiting slow turnover. "Mutations in TIE2/TEK (PI3K/AKT/mTOR pathway) have been identified in venous malformations and blue rubber bleb nevus syndrome." (PMID 38790562, 2024). "However, it is important to note that several studies have reported a recurrence or rebound of venous malformations following sirolimus discontinuation, likely due to reactivation of the mTOR signaling pathway." (PMID 40619100, 2025).
Waldenstrom macroglobulinemia (5 papers, 2010 to 2023). "Therefore, it is critical to examine therapeutic agents that explicitly target both the PI3K/Akt and mTOR signaling cascades in diseases, such as Waldenstrom Macroglobulinemia (WM), that harbor activation of the PI3K/Akt pathway." (PMID 21317453, 2010).
Wilms tumor (5 papers, 2013 to 2025). An embryonal neoplasm characterized by the presence of epithelial, mesenchymal, and blastema components. "The PI3K/AKT/mTOR pathway plays a crucial role in cellular processes and is frequently dysregulated in cancers, including nephroblastoma." (PMID 40771929, 2025). "In Wilm’s tumor, the mTOR pathway is also activated with most tumor cells moderately expressing p-mTOR (Ser 2448) in plasmalemmal and cytoplasmic compartments." (PMID 23922674, 2013). "Some authors assume a relationship between mTOR-pathway activation and Wilms tumor, though the details remain unclear." (PMID 36979978, 2023). "Due to the relationship between ribosomal protein family and PI3K/AKT/mTOR pathway, we hypothesized that NVP-BEZ235 could inhibit nephroblastoma by regulating RPL19." (PMID 40771929, 2025).
acute respiratory distress syndrome (4 papers, 2023 to 2026). Progressive and life-threatening pulmonary distress in the absence of an underlying pulmonary condition, usually following major trauma or surgery. "Additionally, PD-L1 maintains the release of neutrophil extracellular traps by modulating autophagy through the PI3K/Akt/mTOR pathway in acute respiratory distress syndrome." (PMID 38355515, 2024). "Data from animal and human models of non-infectious acute lung injury and acute respiratory distress syndrome indicate that ErbB1 and ErbB2 are key regulators of inflammation and tissue injury via activation of the p38 MAPK, AKT/mTOR, and Ras/RAF/MEK/ERK pathways." (PMID 37581931, 2023).
antiphospholipid syndrome (4 papers, 2019 to 2025). A disorder caused by the presence of autoantibodies directed against phospholipids, causing a hypercoaguable state, which may result in blood clots, stroke, heart attack, and in women, significant pregnancy-related complications, including miscarriage and still birth. "Recent findings suggest that the mTOR signaling pathway may be involved in the vascular lesions associated with antiphospholipid syndrome, as aPLs bind to renal vascular endothelial cells and activate the mTOR complex." (PMID 40141392, 2025). "In addition, involvement of the mTOR pathway in vascular lesions associated with the antiphospholipid syndrome (APS) has also been suggested and may be of high relevance also in SLE." (PMID 30787878, 2019). "Antiphospholipid antibody (aPL)-induced activation of the mTOR (mammalian target of rapamycin) signaling pathway in endothelial cells plays a role in the pathogenesis of vascular lesions in antiphospholipid syndrome (APS)." (PMID 40141392, 2025).
Birt-Hogg-Dube syndrome (4 papers, 2021 to 2025). "Both of these tumour types, thought to be derived from collecting duct type A cells, are almost exclusively diagnosed in older adults, even with the presence of a predisposing germline mutation in mTOR pathway gene FLCN (Birt-Hogg-Dubé syndrome)." (PMID 39271965, 2024). "Patients with Birt-Hogg-Dube syndrome develop a hereditary form of chromophobe nccRCC characterized by the development of tumors with highly active PI3K/mTOR pathways." (PMID 33867192, 2021). "Birt-Hogg-Dubé syndrome (BHDS) is a rare autosomal dominant disorder caused by mutations in the FLCN gene, which encodes folliculin, a tumor suppressor protein involved in cellular energy regulation and mTOR (mammalian target of rapamycin) signaling pathways." (PMID 40589676, 2025). "Germline loss-of-function mutations in mTOR pathway gene FLCN in Birt-Hogg-Dubé syndrome predispose not only to chRCC and RO, but also to more aggressive clear cell and papillary RCCs." (PMID 39271965, 2024).
carcinosarcoma (4 papers, 2014 to 2021). A malignant tumor composed of a mixture of carcinomatous and sarcomatous elements. "To assess mTOR signaling in Trim24COE metaplastic carcinosarcomas at a single-cell level, we performed cytometry by time-of-flight (CyTOF) using allografted tumors." (PMID 34508101, 2021). "CyTOF analysis revealed that Trim24COE metaplastic carcinosarcomas exhibited high levels of TRIM24, phospho-PI3K (pPI3K), phospho-AKT (pAKT), and mTOR within the same spatial orientation." (PMID 34508101, 2021). "Our molecular analyses of Trim24COE metaplastic carcinosarcoma tumors nominated c-MET receptor tyrosine kinase, an upstream activator of PI3K/AKT/mTOR pathways, as a potential therapeutic target." (PMID 34508101, 2021). "c-Met induces up-regulation of PI3K and mTOR pathways at a protein level, consistent with our RPPA and CyTOF analysis of TRIM24COE metaplastic carcinosarcomas." (PMID 34508101, 2021). "To inhibit the PI3K pathway, we used multiple approaches and found that cell viability of primary Trim24COE metaplastic carcinosarcoma cells was reduced in a dose-dependent manner by inhibiting either c-MET, with Critzotinib and PHA-665752, or PI3K/mTOR, with dual inhibitor Dactolisib." (PMID 34508101, 2021). "Using a dual inhibitor developed for human PI3K isoforms and mTOR, we showed that viability of murine TRIM24COE metaplastic carcinosarcoma cells was likewise inhibited, further supporting the parallels between human cancers and tumors arising in the TRIM24COE mouse model." (PMID 34508101, 2021). "This implies that they are important early events in the tumorigenesis of carcinosarcoma and thus could be targeted with PIK3CA/mTOR (Phosphatidylinositol-4,5-Bisphosphate 3-Kinase Catalytic Subunit Alpha /Mechanistic Target of Rapamycin Kinase) inhibitors." (PMID 31324031, 2019).
cerebrovascular diseases (4 papers, 2019 to 2025). "The ability of APOE-ε4 to alter mTOR activity as well as autophagy flux has been suggested to increase the risk for the development of cerebrovascular disease and AD due to possible deficits in synaptic plasticity." (PMID 37238686, 2023). "Furthermore, APOE-ε4 has been shown to affect mTOR signaling, increase mTOR activity, and alter autophagy flux that can increase the risk for the development of cerebrovascular disease and AD." (PMID 37238686, 2023). "Studies have confirmed that the protein kinase B/mTOR pathway plays an important role in developing cerebrovascular diseases." (PMID 34888100, 2021).
co-infection (4 papers, 2016 to 2022). "Overall our findings indicate that mTOR inhibition during Mtb or HIV/Mtb co-infection interferes with phagosomal maturation, thereby supporting mycobacterial growth during low-dose and controlled infection." (PMID 27302320, 2016). "The controlled Mtb infection was disrupted upon mTOR inhibition resulting in increased Mtb replication in a dose-dependent manner which was more pronounced during co-infection." (PMID 27302320, 2016).
cocaine addiction (4 papers, 2019 to 2025). "The present study identifies the mTOR signaling pathway as a promising target for treating cocaine addiction and preventing relapse." (PMID 33897438, 2021). "In this study, rapamycin was administered before the cue-induced drug-seeking behavior test, which verified the role of mTOR activity in the expression of cocaine addiction memory in rats." (PMID 33897438, 2021). "Our results indicate that reactivation of cocaine addiction memory activates the mTOR signaling pathway, and we can deduce that the mTOR signaling pathway is involved in memory reconsolidation." (PMID 33897438, 2021). "miR-677-5p showed enrichment for the cocaine addiction and mTOR signaling pathways and was contained in Hotspot-chr11, which was also enriched for the mTOR signaling pathway." (PMID 31722663, 2019). "Reconsolidation is a protein synthesis-dependent process, thus the mTOR signaling pathway may regulate reconsolidation of cocaine addiction memory through these mechanisms." (PMID 33897438, 2021). "Thus, we speculate that the mTOR signaling pathway may regulate the reconsolidation of cocaine addiction memory by affecting the protein kinase system and cytoskeleton proteins." (PMID 33897438, 2021).
colon adenoma (4 papers, 2010 to 2019). An adenoma that arises from the colon. "The mTOR signalling pathway, whose activation has been functionally linked to the development of many cancers including colonic adenomas, was found to be up-regulated in Hnf1α null intestinal epithelium and could be responsible for the amplification of crypt proliferation and intestinal growth." (PMID 20808783, 2010). "Interestingly, senescence markers from oncogene-induced senescence and mTOR-mediated geroconversion have been detected in pre-malignant lesions, including colon adenomas." (PMID 26744320, 2016).
cystitis (4 papers, 2015 to 2024). Inflammation of the urinary bladder. "Future studies concerning signaling mechanisms of PDGFRα + interstitial cells and their contribution to cystitis should examine downstream kinase targets including mTOR." (PMID 35528149, 2022). "In rodent models of CYP-induced cystitis, functional and pharmacological studies suggest pERK and pAKT may induce pCREB, mTOR, type 1 collagen, and cytokine expression, including IL-6." (PMID 35528149, 2022). "Future studies should examine the effect of imatinib on urothelial barrier function and downstream kinase targets (e.g., mTOR), to further elucidate the mechanism(s) by which imatinib improves urinary bladder function in CYP-induced cystitis." (PMID 35528149, 2022).
desmoid tumor (4 papers, 2013 to 2020). A desmoid tumor (DT) is a benign, locally invasive soft tissue tumor associated with a high recurrence rate but with no metastatic potential. "Sirolimus, a drug that inhibits the mammalian target of rapamycin (mTOR), is currently being evaluated as an anti-cancer agent in desmoid tumor." (PMID 32660036, 2020). "The primary outcome of this trial is to determine if mTOR inhibition is beneficial for children and young adults with desmoid tumors." (PMID 29330550, 2018). "Sirolimus, also known as rapamycin, is an immunosuppressive agent and known mTOR inhibitor, and is currently being investigated in a pediatric desmoid tumor clinical trial (NCT01265030)." (PMID 29330550, 2018).
diabetic neuropathy (4 papers, 2017 to 2025). A chronic, pathological complication associated with diabetes mellitus, where nerve damages are incurred due to diabetic microvascular injury involving small blood vessels that supply these nerves, resulting in peripheral and/or autonomic nerve dysfunction. "Diabetic neuropathy further impacts cellular metabolism by influencing critical pathways such as the mechanistic target of rapamycin (mTOR) and AMP-activated protein kinase (AMPK)." (PMID 40280905, 2025). "In the present study, we explored the effect of 5-HT6 receptor inverse agonists and the potential role of mTOR in painful diabetic neuropathy." (PMID 36830733, 2023). "IGF-1R activation also activates mTOR signaling, which is necessary for the development of painful diabetic neuropathy." (PMID 37242543, 2023). "Constitutive activity of 5-HT6 receptors has been previously shown to be responsible for enhanced mTOR activity in the spinal cord of SNL and OXA rats and remains to be explored in the context of painful diabetic neuropathy." (PMID 36830733, 2023).